PBX3 (PBX homeobox 3)
Description:
Transcriptional activator that binds the sequence 5'-ATCAATCAA-3'.
Tractability: PROTAC: ubiquitination databases record sites on it; its protein half-life has been measured.
Gene: Protein-coding gene on chromosome 9 (125,746,737 to 125,967,377, forward strand). Ensembl gene ENSG00000167081.
Subcellular location: Nucleus
Subcellular location (Human Protein Atlas): Nucleoplasm; Cytosol; Nuclear bodies
Gene Ontology:
Molecular function: DNA-binding transcription activator activity, RNA polymerase II-specific; DNA-binding transcription factor activity, RNA polymerase II-specific; RNA polymerase II cis-regulatory region sequence-specific DNA binding; DNA binding; DNA-binding transcription factor activity; sequence-specific DNA binding
Biological process: animal organ morphogenesis; anterior compartment pattern formation; brain development; embryonic organ development; eye development; neuron development; positive regulation of transcription by RNA polymerase II; posterior compartment specification; regulation of DNA-templated transcription
Cellular component: chromatin; nucleus; transcription regulator complex
Genetic constraint (gnomAD): Loss-of-function variants: 6 observed, 33.26 expected, observed/expected ratio (o/e) 0.18, 90% interval 0.098 to 0.36. The upper end of that interval is the gene's LOEUF score, 0.36, which puts it in group 1 of 6, group 1 being the genes least tolerant of losing a copy. Missense variants: 306 observed, 456.91 expected, observed/expected ratio (o/e) 0.67, 90% interval 0.61 to 0.74. Synonymous variants: 173 observed, 162.97 expected, observed/expected ratio (o/e) 1.06, 90% interval 0.94 to 1.2.
Homologues: Orthologues: chimpanzee PBX3 (100% identical), dog PBX3 (100% identical), guinea pig PBX3 (100% identical), macaque PBX3 (100% identical), pig PBX3 (100% identical), mouse Pbx3 (99% identical), rat Pbx3 (99% identical), tropical clawed frog pbx3 (95% identical), rabbit PBX3 (83% identical), zebrafish pbx3b (75% identical), Drosophila melanogaster exd (62% identical), Caenorhabditis elegans ceh-20 (46% identical), and 5 more. Paralogues in human: PBX1 (84% identical), PBX2 (76% identical), PBX4 (60% identical), MEIS2 (22% identical), MEIS1 (22% identical), PKNOX2 (19% identical), MEIS3 (19% identical), MEIS3P2 (17% identical), PKNOX1 (16% identical), TGIF1 (11% identical), TGIF2 (9% identical), TGIF2LX (8% identical), and 1 more.
Diseases named in the same sentence as PBX3 in open-access papers:
PBX3 is named in the same sentence as 62 diseases in open-access papers, as found by Europe PMC text mining. Sharing a sentence is not in itself a finding about the gene and the disease. The quoted sentences say what the papers report.
leukemia (25 papers, 2005 to 2026). A malignant (clonal) hematologic disorder, involving hematopoietic stem cells and characterized by the presence of primitive or atypical myeloid or lymphoid cells in the bone marrow and the blood. "Up-regulated expression of PBX3 was associated with tumorigenesis and development in malignancies like leukemia and gastric cancer." (PMID 32519740, 2020). "EPZ-5676 downregulates HOXA9/PBX3 expression and induces apoptosis in NPM1-mutated leukemia cells, establishing its therapeutic potential for MLL-r leukemias." (PMID 41199817, 2025). "Targeting PBX3/MEIS1 interaction is a feasible strategy for treating MLL-rearranged leukemia cells overexpressing PBX3." (PMID 38528641, 2024). "MLL1-r and NPM1c leukemias are both associated with upregulated expression of cofactors such as HOXA, MEIS1 and PBX3, which are crucial in leukemia development, cell proliferation, and self-renewal." (PMID 36841758, 2023). "In the same study, PBX3 knockdown delayed leukaemia progression by reducing the LSC potential of MLL‐AF9 leukaemia via promoting LSC apoptosis." (PMID 35068042, 2022). "PBX3 (Pre-B-cell leukemia homeobox 3) had been considered to be a multifunctional oncogene which involved in tumor growth, invasion, and metastasis in leukemia and some solid tumors." (PMID 32047817, 2020). "Targeting HOXA9/PBX3 interaction has been suggested as a new therapeutic strategy to treat leukemia, gastrointestinal cancer, and nonsmall cell lung cancer." (PMID 32047817, 2020). "Recent studies demonstrated that PBX3 acts as an oncogenic gene and participates in tumorigenesis, progression, and metastasis in many human malignancies including leukemia, multiple myeloma, gastrointestinal cancer, and prostate cancer." (PMID 32047817, 2020). "Later, TET1 was verified to promote cell proliferation and induce leukemia by activating the Hoxa9/Meis1/Pbx3 signaling pathway." (PMID 32014008, 2020). "Many of the predicted transcription factors have a known role in hematopoiesis and leukemia development (Ikzf2, Pbx3, and Hoxa13 for upregulated genes and Fos, Nkx2-2, Gata2 for downregulated genes)." (PMID 31186416, 2019). "If MEIS1 potentiates the leukemia action of HOXA9, this is also the case of PBX3, whose expression is also strongly correlated with HOXA9 expression, especially in leukemia subtypes with a normal karyotype or associated with MLL rearrangements." (PMID 31213012, 2019). "Importantly, forced expression of Hoxa9 in combination with the co‐factors Meis1 or Pbx3 alone was sufficient to induce leukemia, establishing those genes as central functional drivers in KMT2A‐rearranged leukemia by shaping the leukemic enhancer landscape." (PMID 39887730, 2026). "In addition, the high expression of PBX3 has been observed in the leukaemia stem cells (LSCs) of MLL‐fusion induced leukaemia." (PMID 35068042, 2022). "The trimeric structure of HOXA9/MEIS1/PBX3 supports HOXA9-driven leukemia." (PMID 33402862, 2020). "Furthermore, our transcription factor binding motif analysis validated that the HVMRs were enriched for motifs with divergent functions, such as ZNF711 for cognitive disability, PBX3 for leukemia and PKNOX1 for adult spermatogenesis." (PMID 31752687, 2019). "However, their expression did not correlate with HOXA5, HOXA7, HOXA9 or MEIS1 and only weakly with PBX3 expression in human leukemia (Spearman, r = 0.37, p = 0.033 and r = 0.44, p = 0.078 respectively)." (PMID 17712416, 2007). "We also measured the Bcat1 mRNA levels in WT, P2x1-null, Pbx3-overexpressing WT or P2x1-null leukemia cells and showed that the Bcat1 mRNA level was significantly downregulated in P2x1-null AML cells, while increased in Pbx3-overexpressing leukemic cells." (PMID 36418376, 2023). "In human leukemia, the cooperation between MEIS1 and HOXA9 with PBX has been extensively reported; specifically, the PBX3 form appears to be the prevalent form involved." (PMID 34698191, 2021).
leukemia (continued). "It is possible that the dependence of MLL-r, FLT3-ITD+ leukemia on FLT3-ITD expression may be due to HOXA9 requiring STAT5A and/or PBX3 and C/EBPA to cooperatively bind select target genes." (PMID 34263728, 2021). "PBX3 (not PBX1 or PBX2) is apparently the most important form of PBX that interacts with MEIS1 in human MLL-r leukemias." (PMID 34698191, 2021). "Ash1l, Ctnnb1, Hoxa7, and Hoxa9 were also upregulated in the single mutant Mir-142−/− GMPs compared to WT, but the key co-factors Meis1 and Pbx3 were not, potentially explaining why these mice failed to develop leukemia." (PMID 33173219, 2020). "The presence of PBX3 and MEIS1 increases HOXA9-induced leukemia." (PMID 33402862, 2020). "While Hoxa genes were upregulated in Mir142−/− GMPs, Meis1 and Pbx3 were not, consistent with the failure of these mice to develop leukemia." (PMID 33173219, 2020). "For example, in NUP98-HOXD13-transformed AML, PBX3 was found to be necessary for the continued proliferation and survival of malignant cells, and suppression of PBX3 transcription through inhibition of the H3K79 methylase blocked the proliferation of NPM1-driven leukemia." (PMID 32069812, 2020). "A similar approach using a mouse model of leukemia development revealed that this oncogenic role was specific to PBX3, as neither PBX1 nor PBX2 could substitute for it in forced expression experiments." (PMID 32069812, 2020).
colorectal cancer (20 papers, 2015 to 2023). A primary or metastatic malignant neoplasm that affects the colon or rectum. "Our purpose is to assess the association between PBX3 methylation in PBLs and colorectal cancer (CRC) prognosis." (PMID 31140752, 2019). "Overexpression of PBX3 has been associated with many kinds of malignancies, including gastric cancer, colorectal cancer, prostate and leukemic." (PMID 28934982, 2017). "Recent reports have shown the oncogenic role of PBX3 in hematological malignancies and a variety of solid tumors, including acute myeloid leukemia, gastric cancer, colorectal cancer, liver cancer, and cervical cancer 18-22." (PMID 37781025, 2023). "In colorectal cancer, PBX3 is induced by WNT activation and by the EMT transcription factors SNAIL and ZEB1." (PMID 35509064, 2022). "The high expression of PBX3 in colorectal cancer can be activated by mitogen-activated protein kinase/extracellular signal-regulated kinase signaling, which induces cell invasion and migration." (PMID 35342419, 2022). "Notably, the main EMT-associated genes dysregulated upon upregulation of PBX3 in HCC were different from those dysregulated in colorectal cancer and in gastric cancer upon upregulation of PBX3, indicating that PBX3 could activate a novel EMT-related pathway in HCC." (PMID 35509064, 2022). "Except for the reported oncogenic role of PBX3 in AML, upregulated PBX3 has also been found in other cancers, such as gastric cancer, colorectal cancer, liver cancer, glioma, etc., that is related to the malignant transformation and poor prognosis." (PMID 34006845, 2021). "A previous study implied that PBX3 strengthened cell metastasis via the MAPK signaling pathway in colorectal cancer." (PMID 34001137, 2021). "PBX3 was also shown to be necessary for EMT in colorectal cancer cells, and is upregulated by the SNAIL and Zeb1 EMT-associated transcription factors, possibly through an indirect mechanism involving suppression of the PBX3-targeting miR-200c." (PMID 32069812, 2020). "Previous report had shown that PBX3 induced migration and invasion of colorectal cancer cells partially through activation of ERK pathway." (PMID 32047817, 2020). "Overexpression of PBX3 induces epithelial-mesenchymal transition and promotes invasion and metastasis of gastric, and colorectal cancer cells." (PMID 32047817, 2020). "Many reports demonstrated that aberrant expression of PBX3 was closely correlated with survival and tumor growth in patients with gastric and colorectal cancer." (PMID 32047817, 2020). "The first indication of a role of PBX3 in colorectal cancer was the finding that lower tumor expression of the miR-let-7c was associated with increased metastases, increased grade, and shorter survival." (PMID 32069812, 2020). "PBX3 protein, in particular, contributes to cell proliferation, invasion, and metastasis in colorectal cancers by modulating mitogen-activated protein kinases (MAPK)/extracellular-signal-regulated kinase (ERK) signaling pathways." (PMID 33402862, 2020). "In colorectal cancer, pre-leukemia transcription factor 3 (PBX3) induces the MAPK/ERK pathway to improve the invasiveness of cancer cells." (PMID 31547193, 2019). "PBX3 was also reported to be a direct target of let‐7c, which could then bind to the 3’UTR of PBX3 and inhibit its expression in colorectal cancer." (PMID 35068042, 2022). "Notably, PBX3 was reported to be a novel indicator of EMT in colorectal cancer, and it was reported to possibly be regulated by multiple miRNAs and to be essential for liver tumor-initiating cells." (PMID 35509064, 2022). "Additionally, previous study has demonstrated that PBX3 can promote EMT-related gene transcription in colorectal cancer and gastric cancer." (PMID 35509064, 2022). "Furthermore, PBX3 has been reported to have an oncogenic role in promoting cell proliferation and migration, such as in glioblastoma or colorectal cancer." (PMID 35509064, 2022).
colorectal cancer (continued). "Moreover, PBX3 expression was strongly related with lymph node invasion and poor prognosis in colorectal cancer." (PMID 32519740, 2020). "In colorectal cancer, PBX3 mRNA was negatively correlated with Let-7c levels so that PBX3 could reverse the suppression growth effects of Let-7c." (PMID 25875009, 2015). "Additionally, PBX3 is overexpressed in other cancers, such as gastric and colorectal cancers." (PMID 29324665, 2018). "The same study demonstrated that miR-let-7c targets PBX3, as well as K-Ras and MMP11, in the colorectal cancer-derived cell line LoVo." (PMID 32069812, 2020). "Recently, high PBX3 expression was proved to be promoted by Wnt activation, SNAIL and ZEB1 through the indirect mediation of miR-200 in EMT induction of colorectal cancer." (PMID 31547193, 2019). "Also, hsa-let-7c inhibits metastasis in colorectal cancer, and its downregulation stimulates the expression of K-RAS, MMP11, and PBX3 and promotes cell migration, glioblastoma, and invasion." (PMID 35490305, 2022). "PBX3 protein, which forms a heterodimer with MEIS proteins, is overexpressed in colorectal cancers." (PMID 33402862, 2020). "Studies have revealed that PBX3, the homologous family protein of PBX1, promoted the migration and invasion of glioblastoma and colorectal cancer via activation of the MAPK/ERK signaling pathway, which might bring new insights into the oncogenic role of PBX1 in NSCLC." (PMID 36361531, 2022).
gastric cancer (17 papers, 2015 to 2025). A primary or metastatic malignant neoplasm involving the stomach. "PBX3 has also been shown to be upregulated in gastric cancer cells, and that this was associated with greater invasion depth, and advanced clinical stage and tumour grade." (PMID 28423659, 2017). "Through the miR-145-5p/PBX3 axis, circTRPM7 improved the inhibitory effect of sinomenine on the development and metastasis of gastric cancer cells." (PMID 39314750, 2024). "CircCDR1 and circHECTD1 via miR-7-5p/REGγ and miR-137/PBX3 axis affected the role of Diosbulbin-B in the prevention and treatment of gastric cancer." (PMID 39314750, 2024). "In gastric cancer, PBX3 promotes the activation of the AKT pathway, subsequently facilitating the EMT transition." (PMID 35509064, 2022). "More recently, miR-320a was also shown to have a tumor-suppressive role in gastric cancer through targeting PBX3, and that the expression of this miR in gastric cancer was repressed in part by methylation of its promoter." (PMID 32069812, 2020). "The overexpression of PBX3 in gastric cancer cell lines with low endogenous PBX3 expression accelerated cell proliferation and increased colony formation and cell-invading ability." (PMID 28423659, 2017). "Recently, PBX3 was reported to be upregulated in gastric cancer and to regulate tumor cell proliferation." (PMID 28934982, 2017). "The proto-oncogene PBX3 is over-expressed in gastric cancer, and its expression levels are positively correlated with advanced invasion depth, clinical stage and grade of tumor differentiation." (PMID 27285759, 2016). "The expression of PBX3 in gastric cancer is closely related to the clinical stage, invasion depth, and differentiation degree of tumors, and the overexpression of PBX3 can promote the proliferation and clonal formation of gastric cancer cells." (PMID 35342419, 2022). "PBX3 is highly expressed in gastric cancer, endometrial cancer, and other tumors." (PMID 35342419, 2022). "PBX3 facilitated cell proliferation and colony formation ability in gastric cancer." (PMID 32519740, 2020). "Recently, PBX3 was found to be overexpressed in gastric cancer and to regulate cell proliferation." (PMID 25875009, 2015). "The overexpression of PBX3 also resulted in an increase in MMP9 activity, a key protease involved in metastasis, as well as an increase in the ability of gastric cancer cells to promote tubule formation by HUVEC cells, indicating an increase in pro-angiogenic signaling." (PMID 32069812, 2020).
hepatocellular carcinoma (12 papers, 2016 to 2025). A malignant tumor that arises from hepatocytes. "PBX3 was closely associated with the stemness of hepatoma cells, and its degradation was in ubiquitin‐proteasome system‐independent manner." (PMID 35068042, 2022). "Loss of exosomal miR-320a from CAFs mediated EMT in hepatocellular carcinoma cells by binding to its direct downstream target PBX3." (PMID 30646925, 2019). "The degradation of PBX3 protein was reported to be independent of the ubiquitin-proteasome system but instead associated with miRNAs in hepatoma cells." (PMID 35509064, 2022). "Furthermore, miR-320a in exosomes derived from cancer-associated fibroblasts can suppress cell proliferation, migration, and metastasis in hepatocellular carcinoma through competitively binding to its target gene PBX3." (PMID 32528301, 2020). "In addition, in hepatocellular carcinoma (HCC) cells, PBX3 was found to mediate the effect of miR‐302A on cell proliferation and apoptosis by targeting the expression of p‐p38, p‐ERK1/2 and p‐JNK." (PMID 35068042, 2022). "In conclusion, miR-302a inhibited proliferation and promoted apoptosis in human hepatoma cells by targeting MAP3K2 and PBX3." (PMID 30765768, 2019).